NRP1 (neuropilin 1)
Diseases named in the same sentence as NRP1 in open-access papers (continued):
Sharing a sentence is not in itself a finding about the gene and the disease.
breast carcinoma (continued). "In SEMA3A-expressing breast cancer cells, an autocrine feedback loop activates the serine/threonine kinase GSK-3 via NRP1 and thus the expression of integrin α2β1, thereby attenuating migration and invasion." (PMID 30717262, 2019). "We conclude that NRP-1 expression in breast tumor tissue, post-NAC, is a potential predictive biomarker for breast cancer survival." (PMID 31106153, 2019). "We used MCF7 and T47D human breast cancer cell lines that are ER positive, sensitive to Tam and express NRP-1 to study the interactions of FAM-labeled iRGD-guided and control PS with the cultured breast cancer cells." (PMID 31812165, 2019). "The role of Neuropilin-1 (NRP-1), a multifunctional transmembrane protein that interacts with a multitude of signaling receptors, in breast cancer pathogenesis has been extensively investigated." (PMID 29728077, 2018). "Inhibition of NRP1 by a blocking antibody prevents tumor growth increased by VEGF-A in a mouse model, suppresses mammosphere formation by breast cancer stem-like cells, and impairs the invasion of glioblastoma." (PMID 29659486, 2018). "In conclusion, we demonstrated that HS3ST3B enhances the proliferation and survival of breast cancer MDA-MB-231 cells, via a mechanism that is dependent on Nrp1." (PMID 30360368, 2018). "Conversely, in PBMCs, NRP-1 and its interacting molecules SEMA4A and SNAI1 are significantly downregulated in breast cancer patients compared to healthy controls, indicating a protective role." (PMID 28607365, 2017). "Secondly, this study implies the protective role of NRP-1, SNAI1 and SEMA4A expression in PBMCs in healthy controls and early stage breast cancer patients." (PMID 28607365, 2017). "For example, overexpression of miR-206 was used to treat breast cancer cells to inhibit the downstream genes of transforming growth factor (TGF)-β, such as NRP1 and SMAD2, to reduce the migration and invasion of breast cancer cells." (PMID 28701377, 2017). "We showed that the expression of Nrp1 is enriched in Procr+ MaSCs, and that Nrp1 plays an essential role in MaSC property maintenance and MMTV-Wnt1 mammary tumor growth." (PMID 28887477, 2017). "Barr and co-workers demonstrated in 2005 that a peptide targeting the VEGF165-binding site of NRP1, antagonises the autocrine anti-apoptotic effects of VEGF in cultured 4T1 and MDA-MB-231 breast carcinoma cells." (PMID 27351129, 2016). "Through correlation analysis of gene expression profiles between candidate genes and miR-148a in the TCGA breast cancer patient database, we further narrowed down targets of miR-148a to four genes, INHBB, PIK3C2B, WNT1 and NRP1." (PMID 26967387, 2016). "Neuropilin 1 knockdown using siRNA inhibited breast carcinoma cell migration 23, and a peptide targeted to the VEGF binding site of NRP1 induced breast tumour cell apoptosis." (PMID 26147006, 2015). "Assessment of cyclin D1, FOXP1, NRP1 and CD99 expression was repeated on a validation cohort of 82 BRCA1 and 65 sporadic basal-like breast cancers." (PMID 26152113, 2015). "NRP-1 expression is increased by a glycoprotein named transmembrane NMB (GPNMB), which is known to promote malignant phenotype in breast cancer." (PMID 26558271, 2015). "The 7 angiogenesis genes present in the list were also predominantly down-regulated (e.g. NRP1, JMJD6, CYR61, FGFR1) and again the impact of these genes on the carcinogenesis of breast cancer cells has been described." (PMID 21062462, 2010). "In a breast cancer study, NRP1 overexpression was found to interfere with the m6A-dependent downregulation of the Bcl-2 mRNA via WTAP and improve DNA repair ability, which in turn protects breast cancer cells from apoptosis and promotes radioresistance." (PMID 39972266, 2025). "Our previous study found that the VEGF/NRP-1 axis may be involved in the regulation of migration, invasion, and EMT transformation in breast cancer." (PMID 38169627, 2024).
breast carcinoma (continued). "However, circulating NRP-1 levels were studied in early breast cancer, and patients with low NRP-1 levels at baseline had a significantly better breast cancer-specific survival than patients with high NRP-1." (PMID 38468231, 2024). "Although Collagen Alpha-3 (VI) COL6A3 was shown to enhance brain metastasis in breast cancer patients, COL6A3 was upregulated in NRP-1 KO cells which showed less metastatic lesions to the lungs; future gain and loss of function studies will reveal more information about the actual role of this gene." (PMID 37175499, 2023). "The results we obtained in this and our previous studies support further exploring the strategy of targeting NRP-1 in breast cancer treatment, either with or without targeting the VEGF pathway since we showed that other genes can be targeted instead." (PMID 37175499, 2023). "Here we demonstrate the presence of NRP2a and NRP2b in macrophages, the co-enrichment of both isoforms in TAMs within murine and human breast cancer and speculate that NRP2 and NRP1 denote unique TAM subsets." (PMID 35651620, 2022). "Nonetheless, after stratification according to menopausal status, the serum levels of VEGF and NRP-1 were not modified between breast cancer patients and the control group." (PMID 35887839, 2022). "To investigate whether RP11-70C1.3 facilitated breast cancer chemoresistance through a miR-6736-3p/NRP-1-dependent manner, we constructed NRP-1-overexpressing vector pcDNA3.1-NRP-1." (PMID 34374639, 2022). "As observed in mouse mammary tumors, macrophage subsets which expressed high levels of NRP2Total and NRP2b did not express significant NRP1, suggesting that NRP1 and NRP2 are associated with discrete macrophage populations in human breast cancer MPEs." (PMID 35651620, 2022). "Moreover, we demonstrate that miR-29b-2 directly targets VEGF-A while miR-338 directly targets NRP1, and show that regulation of miR-29b-2 and miR-338 mediates the ability of FOXO3a to suppress VEGF-A/NRP1 signaling and breast cancer metastasis." (PMID 33262463, 2021). "Thus, our results indicated that FOXO3a is a negative regulator of VEGF-A/NRP1 and that dysregulated FOXO3a/VEGF-A/NRP1 signaling contributes to disease progression of breast cancer." (PMID 33262463, 2021). "A recent study suggests that NRP-1 may be an independent prognostic factor for TNBC patients and increased NRP-1 expression has been observed after neoadjuvant chemotherapy in breast cancer patients." (PMID 33912463, 2021). "In breast cancer, particularly TNBC, NRP-1 is an isoform-specific receptor for VEGF and the VEGF/NRP-1 axis promotes cell proliferation and migration by increasing the activity of cell division control protein 42 homolog (Cdc42) or enhancing the EMT and activation of NF-κB and β-catenin." (PMID 33912463, 2021). "Therefore, our study suggests an important role of FOXO3a in inhibiting breast cancer metastasis and provides a previously undescribed mechanism of FOXO3a-mediated repression of VEGF-A/NRP1." (PMID 33262463, 2021). "Moreover numerous targets of miR‐148a‐3p have been identified in breast cancer, including ALCAM, NRP1, SMAD2, and SPIN1, they mainly function in regulating cell growth, metastasis, and adhesion." (PMID 32508020, 2020). "Moreover, anti-NRP1 antibody was found to inhibit the formation of NRP1/α5β1 integrin complexes, as well as phosphorylation of FAK and p130cas, in breast cancer cell lines." (PMID 31027288, 2019). "In addition, we recently reported that NRP-1 overexpression was induced by a combination of Adriamycin and cyclophosphamide-treated BT474 breast cancer cells." (PMID 31106153, 2019). "Moreover, NRP1 influences the binding response of integrin αvβ3 to tenascin C, an adhesion-modulating ECM-protein, in breast cancer cells." (PMID 30717262, 2019). "NF-κB is known to drive NRP-1-mediated EMT and migration in breast cancer." (PMID 29728077, 2018).
breast carcinoma (continued). "Metastatic breast cancer patients displayed upregulated plasma NRP-1 compared to healthy controls (p = 0.028), although univariate analysis also indicated increased plasma NRP-1 in non-metastatic breast cancer patients compared to healthy controls." (PMID 28607365, 2017). "On the contrary, the decreased expression of NRP-1 in addition to SNAI1 and SEMA4A in PBMCs in the cancer cohort studied compared to healthy controls highlights their potential protective role against breast cancer." (PMID 28607365, 2017). "Tumor tissue expression of NRP-1, but not PlGF, was significantly upregulated in metastatic breast cancer (n = 15) compared to non-metastatic cases (n = 52, p = 0.016)." (PMID 28607365, 2017). "Besides prostate cancer PC3 cell model, we also detected similar pharmacological effects of NDGA on NRP1 expression and cell migration in breast cancer MDA-MB-231 cells, which also show high level of NRP1 expression and cell migration." (PMID 27863391, 2016). "In renal cell carcinoma, the VEGF-A/NRP1 signal was found to activate Ras and promote tumor growth in vivo, while VEGF-A/NRP1 signals induced the phosphorylation of Akt leading to breast cancer cell survival." (PMID 26209534, 2015). "The other target receptor, NRP1, was not differentially expressed in any breast cancer subtypes in TCGA, but was overexpressed in basal breast cancer relative to other subtypes in METABRIC (p-value of 2 × 10−4)." (PMID 26173622, 2015). "Tumor cell expression of NRP1 was also observed in 36% of primary lung carcinomas and 6% of primary breast carcinomas, but no colorectal adenocarcinomas." (PMID 24708840, 2014). "For instance, in breast cancer biopsies Nrp1 expression is a feature of high grade tumours, rather than low grade, and is frequently expressed by tumours of patients who died from cancer." (PMID 22948112, 2012). "In contrast, EG3287 caused no alterations in the cytotoxic effects of 5-FU in breast carcinoma MDA-MB-453 cells, which are NRP1-negative." (PMID 20087344, 2010). "The activation of an autocrine loop of VEGF-A signaling required for breast carcinoma invasion in vitro, is mediated by the receptor Neuropilin-1(Nrp-1), but not the receptor Flt-1." (PMID 19226458, 2009). "A recent study has shown that VEGF-165 acts as an autocrine survival factor in NRP-1-positive breast carcinoma cells lacking VEGFR-2 and that this likely occurs through activation of the PI-3 kinase pathway." (PMID 12618892, 2003). "Studies have shown that radiotherapy alone significantly increases double-strand DNA (dsDNA) damage in breast cancer (BC) cells, whereas NRP1 overexpression combined with radiotherapy does not significantly affect dsDNA breaks, indicating that NRP1 plays a key role in BC radioresistance." (PMID 40823093, 2025). "The downregulated C-C motif chemokine ligand 20 (CCL20) in NRP-1 KO cells was also studied in taxane-containing chemotherapy in triple-negative breast cancer (TNBC), and the elevated levels of CCL20 were shown to stimulate breast cancer stem-like cells through protein kinase C (PKC)." (PMID 37175499, 2023). "Breast cancer cells that lacked NRP-1 failed to migrate to the lungs." (PMID 37175499, 2023). "Similarly, the NRP-1 knockout MDA-MB-231 cells displayed a significant decrease in the levels of integrin β3 (ITGB3), another extracellular adhesion protein well-known to enhance lung and bone metastasis of breast cancer cells once upregulated." (PMID 37175499, 2023). "Moreover, the concentration of NRP-1 remained relatively invariable between overweight/obese and non-obese breast cancer patients." (PMID 35887839, 2022). "However, a more detailed role of NRP-1 upregulation in breast cancer pathogenesis has not been fully elucidated." (PMID 34374639, 2022).
breast carcinoma (continued). "Therefore, our result confirms the usefulness of the strategy to target NRP-1 in combination with chemotherapy in patients with a partial response to NAC alone, which thus determines that NRP-1 is a pharmacodynamic biomarker in breast cancer." (PMID 31106153, 2019). "In the last few months alone, expression of NRP1 has been reported in a variety of cancers, including oral squamous cell carcinoma, gastric cancer, pancreatic duct adenocarcinoma (PDAC), hepatocellular carcinoma, cholangiocarcinoma, colorectal carcinoma, prostate cancer, and breast cancer." (PMID 30717262, 2019). "The dependence of NRP-1 on integrin signaling was not previously reported in breast cancer." (PMID 29728077, 2018). "The role of NRP-1 in breast cancer-related chemoresistance has not been previously explored." (PMID 29728077, 2018). "Breast cancer patients with advanced diseased nodes N3 displayed significantly higher plasma NRP-1 compared to patients with no nodal metastasis N0 (p = 0.003), less advanced nodal metastasis N1 (p = 0.023) and N2 (p = 0.018) and to healthy controls (p = 0.002)." (PMID 28607365, 2017). "Similar to observations in the plasma, breast cancer cases with advanced nodal metastasis N3 (n = 14) have higher tumor NRP-1 tissue expression compared to cases with no nodal metastasis (n = 18, p = 0.041) or N1 (n = 22, p = 0.023) disease, as indicated by both multivariate and univariate analysis." (PMID 28607365, 2017). "These trends were particularly contrasting in the plasma profile since all the markers quantified in plasma i.e. NRP-1, VEGF, TGFβ1 and PlGF indicated opposing trends in early onset breast cancer vs older cases, with comparable variability in both healthy controls and breast cancer cases." (PMID 28607365, 2017). "While it is known to augment angiogenesis through enhancing the binding of VEGF to VEGF-R2 on endothelial cells, it has also been shown to play an essential role in autocrine anti-apoptotic signalling by VEGF in NRP-1 positive breast cancer cells lacking VEGF-R2." (PMID 20950431, 2010). "Hence, targeting the TMD of NRP1, with a peptide mimicking its TMD could be a future potent drug in breast cancer therapy particularly to prevent metastasis formation by administrating long term low dose MTP-NRP1 upon reduction or surgical removal of the primary tumor." (PMID 27351129, 2016). "GPNMB drives an increase in NRP1 levels, which in turn potentiates VEGF signaling in breast cancer cells to mediate the growth but not metastasis of these cells in an in vivo experimental model." (PMID 37894289, 2023). "Regarding the BMI values among breast cancer molecular subtypes, the Luminal A patients who were overweight/obese had elevated serum levels of VEGF, HB-EGF, PDGF-CC and NRP-1 when compared to the non-obese patients (p > 0.05)." (PMID 35887839, 2022). "Our analysis showed that PLXNA3, B2, and C1 were significantly upregulated, and NRP1, NRP2, PLXNA1, A2, A4 were significantly downregulated, while the rest of the members (PLXNB1, B3 and D1) were not differentially expressed in breast cancer tumors." (PMID 32640719, 2020). "It is important to note that the plasma levels of NRP-1, PlGF, VEGF and TGF-β were not significantly different between the breast cancer patients and healthy controls in the studied cohort." (PMID 28607365, 2017). "In vitro, exogenous Sema3f inhibits cell attachment and spreading in the breast cancer cell line MCF7, a line that expresses Nrp1 but not Nrp2; this inhibition is blocked by the addition of anti-Nrp1 functional blocking antibody." (PMID 22783168, 2012). "However, the effect of NRP-1 overexpression on the ITGB3 signaling pathway and its role in chemoresistance in breast cancer has not yet been investigated." (PMID 29728077, 2018).
breast carcinoma (continued). "Despite the numerous roles of NRP-1, global transcriptomic effects elicited by NRP-1 in cancer cells have not been previously explored and more importantly, its role in the response to chemotherapy in breast cancer has not been investigated either." (PMID 29728077, 2018). "Peptides targeting NRP-1 have been shown to induce apoptosis in human and murine breast cancer cells as well as endothelial cells, while a peptide targeting VEGFR2 only inhibited the growth of endothelial cells and did not affect the viability of breast cancer cells." (PMID 37175499, 2023). "Thus, NRP1 mediates the chemotaxis and survival of VEGF autocrine functions in breast carcinoma MDA-MB-231 cells lacking VEGFR-2, and in Dunning rat prostate carcinoma AT2.1 cells, which do not express VEGFR-2, NRP1 overexpression increases cell migration and reduces cell apoptosis in vivo." (PMID 20087344, 2010).